CRP (C-reactive protein)
Diseases named in the same sentence as CRP in open-access papers (continued):
Sharing a sentence is not in itself a finding about the gene and the disease.
COVID-19 (continued). "In COVID-19 patients, chemerin positively correlated with C-reactive protein, alkaline phosphatase, eosinophils, and lymphocytes in the entire cohort, as well as after excluding patients with liver cirrhosis and patients with arterial hypertension." (PMID 39335612, 2024). "This study identified NMR, NLR, CRP, IL6, and DD as factors associated with the risk of COVID-19-related death using LASSO regression." (PMID 39555074, 2024). "Even though the hs-CRP value was established at <10 mg/L to demonstrate that there was no acute infection, it appears that cellular inflammation occurs post-COVID-19." (PMID 38550672, 2024). "This study identified five blood markers (NMR, NLR, CRP, IL6, and DD) that were significantly associated with the risk of death in patients with COVID-19." (PMID 39555074, 2024). "In univariable analysis, we found that white blood cell, NLR, IL-6, CRP, LDH, D-dimer, PT level were all associated with COVID-19 elderly patients combined with respiratory failure." (PMID 39416623, 2024). "The severity of COVID-19 has also been determined by serum biomarkers such as interleukin-6 (IL-6), CRP, ferritin, and lactate dehydrogenase due to their influence in the inflammatory process, leading to SARS-CoV-2 aggravation." (PMID 38687065, 2024). "We report that the levels of ferritin, hepcidin, zinc, CRP, and IL-6 are higher in patients with COVID-19 in the ICU in the intergroup comparison in both the higher altitude region and the lower altitude region." (PMID 39062181, 2024). "This study identifies 4 predictors of COVID-19 mortality, inflammatory markers (CRP), coagulation function (PT-INR), and Lactate at admission are risk factors for prognosis, patients with Ambavizumab-romivizumab therapy have a better prognosis." (PMID 39315175, 2024). "This study showed that there were significantly elevated levels of LDH, D-dimer, serum ferritin, and CRP across the three age groups of COVID-19 patients." (PMID 39195007, 2024). "In the convalescent phase of COVID-19, the inflammatory responses subside, as indicated by low levels of CRP, an inflammatory marker, in both HMo and NMo cases in this study." (PMID 39628664, 2024). "Other inflammatory biomarkers, including CRP and IL-6, have been extensively investigated and used in daily in-hospital practice for patients with COVID-19." (PMID 38982355, 2024). "At baseline COVID-19 patients had high CRP levels, which were comparable in the study groups (p = 0.15)." (PMID 38750098, 2024). "Previous reported modification in severe forms of COVID-19 showed increased levels of C-reactive protein, interleukin-6, and D-dimers to predict mortality in hospitalized COVID-19 patients." (PMID 40376291, 2024). "Older age, longer length of hospitalization, longer duration of mechanical ventilation, tracheostomy, diabetes, and higher levels of CRP and PCT were associated with oral intake difficulty in patients with severe COVID-19." (PMID 38514734, 2024). "Initial blood analyses on COVID-19 diagnosis showed that patients with both AP and periodontitis had higher CRP, ferritin, urea, HbA1c, WBC, and creatine levels than healthy patients." (PMID 38246829, 2024). "Patients with severe COVID-19 had higher CRP, procalcitonin, ferritin, and LDH levels in comparison to patients with moderate disease." (PMID 38791005, 2024). "Currently, this is the first study to evaluate the relationship between CRP rs1205 and rs1800947 and COVID-19 mortality." (PMID 38184750, 2024). "In this study, we demonstrate that C-reactive protein determination can predict the response to tocilizumab in severe COVID-19, the target patients for treatment with this drug." (PMID 38687065, 2024). "Receiver operating characteristic (ROC) curve analysis was used to determine the best cutoff values for C-reactive protein (CRP) that can be used to estimate the severity of COVID-19." (PMID 39407172, 2024).
COVID-19 (continued). "A multi-center cohort study enrolling 239 COVID-19 patients observed disease progression in ~ 40% of the patients in the hospital, identifying CRP levels > median value of (OR, 2.25; 95% C.I., 1.02–4.99) as an independent risk factor for progression." (PMID 39402606, 2024). "The majority of COVID-19 patients in a Chinese prospective cohort analysis exhibited increases in CRP, ESR, and LDH, whereas 44.9% of patients had proteinuria, 14.1% had a high level of creatinine, and 13.1% had an elevated BUN level." (PMID 39995847, 2024). "On 6 December 2021, it received approval recommendations for patients “with severe COVID-19 who required extra oxygen or mechanical ventilation and had high levels of C-reactive protein in the blood”." (PMID 38248262, 2024). "As an inflammatory biomarker, CRP is related to the development of COVID-19 and is an early predictor of severe disease." (PMID 38104038, 2024). "Of note, the Q-values were less significant for IL-6 or CRP (-log10 35.81 and 108.3, respectively, p<0.00001 for both), which are two common biomarkers of COVID-19 severity." (PMID 39835130, 2024). "Decrease in calprotectin and C-reactive protein levels, IL-6 in hospitalized patients supplemented with probiotics corroborated their beneficial role in COVID-19." (PMID 38178223, 2024). "In terms of immune biomarkers, MSC treatment inhibited inflammation responses in COVID-19 patients, as was indicated by the decreased levels of CRP and IL-6." (PMID 38851730, 2024). "This is consistent with previous findings of elevated CRP levels in the serum of COVID-19 patients being correlated with COVID-19 severity, suggests it as a potential early marker for predicting disease severity." (PMID 39375263, 2024). "For instance, plasma levels of serumamyloid A protein, C-reactive protein, Alpha-1-acid glycoprotein 1,mannose-binding protein C, haptoglobin, and attractin were significantly elevatedin the COVID-19-related AVB group." (PMID 39076308, 2024). "Our data also confirmed that the levels of CRP, ferritin, procalcitonin, and D-dimer were increased in patients with severe COVID-19." (PMID 39519310, 2024). "The present study confirmed this result as the CRP level was significantly higher in patients who died from COVID-19 (P < 0.01), with an AUC of 0.816." (PMID 39555074, 2024). "Prior studies on the innate immune response in COVID-19 patients have noted an increase in total neutrophils, serum interleukin-6 (IL-6), and C-reactive protein (CRP), along with a decrease in total lymphocytes." (PMID 38655258, 2024). "In a metanalysis of 32 studies involving 10 491 COVID-19 patients, lymphopenia (3.33, p<0.00001), elevated CRP (OR 4.37, p<0.00001), D-dimer (3.39, p<0.00001) and PCT (6.33, p<0.00001) concentrations were independent markers of poor outcomes." (PMID 39009040, 2024). "Because SARS-CoV-2 infection-induced cytokine storm plays a key role in the COVID-19 pathogenesis, we compared differences in CRP and IL-6 levels in serum derived from both CB and maternal blood." (PMID 39574146, 2024). "In patients with severe COVID-19, ferritin, C-reactive protein (CRP), procalcitonin, and lactate dehydrogenase (LDH) levels were higher than those in patients with moderate disease." (PMID 39273246, 2024). "Significant increases in CRP can be seen in acute COVID-19 patients; however, PACS patients experience high CRP levels for several months after the first contact with SARS-CoV-2, increasing the risk of multi-organ damage." (PMID 39200115, 2024). "Due to the abundant expression of ACE2, COVID-19 can induce tissue injury and immune dysregulation, resulting in highly elevated levels of inflammatory cytokines, such as IL-6 and CRP, as well as increased NLR." (PMID 37702601, 2024). "This study aims to investigate the impact of COVID-19 on psychiatric patients, focusing on factors such as their vaccination status, comorbidities, medication regimens, and biomarkers like C-reactive protein (CRP) and ferritin." (PMID 39408010, 2024).
COVID-19 (continued). "Patients treated at the ICU were more likely to have cardiovascular and respiratory symptoms, as well as a history of symptomatic COVID-19, higher C-reactive protein (CRP), PCT, BNP and lower albumin levels." (PMID 39596959, 2024). "On the other hand, apparently in COVID-19 patients, high levels of CRP are responsible for decreasing vitamin D levels, making it a “negative acute phase reactant”." (PMID 38672258, 2024). "With regard to biomarkers, COVID-19 and TB present elevated levels of C-reactive protein, D-Dimer, and interleukin 6, but also alterations such as leukopenia, neutrophilia or even platelet dysfunctions." (PMID 38793006, 2024). "For example, elevated serum ferritin and C-reactive protein (CRP) levels are commonly observed in patients with severe COVID-19 and sHLH." (PMID 38360719, 2024). "Hepcidin, ferritin, CRP, and IL-6 are predictive parameters of critical COVID-19 occurrence, and extremely high levels of IL-6 are strongly associated with the presence of septic shock or sepsis in COVID-19 patients." (PMID 39457607, 2024). "Pro-inflammatory markers such as high CRP (C-reactive protein), procalcitonin, and ferritin have been found to be elevated in both COVID-19 and diabetes." (PMID 38350147, 2024). "In this study, it was found that there was a marked reduction in CRP levels in COVID-19 patients following corticosteroid therapy." (PMID 38304653, 2024). "This study consistently demonstrates that inflammatory indicators CRP and PCT are associated with the prevalence of hyperglycemic crises in T2DM patients with COVID-19, confirming the significant role of inflammation in the pathogenesis of ADC in COVID-19." (PMID 38455656, 2024). "The COVID-19-infected HS group exhibited significantly soaring concentrations of c-reactive protein (CRP), D-dimer, and ferritin compared to the MS category." (PMID 38610151, 2024). "All of the CE species analyzed in our study cohort were negatively correlated with CRP, most of them with procalcitonin and some with IL-6 and ferritin in severe COVID-19." (PMID 39051245, 2024). "More recent studies carried out in severe COVID-19 patients show that the CRP/TTR ratio is adequate to predict the severity of the disease upon admission and during hospitalization." (PMID 39125329, 2024). "The Mann-Whitney U-test was used to compare PCT and CRP between the COVID-19 and non-COVID-19 groups." (PMID 38172766, 2024). "Intriguingly, a notable elevation in CRP levels was observed among the COVID-19 patients in some studies, corroborating findings from other research." (PMID 38611597, 2024). "The severity of COVID-19 was determined based on the extent of lung involvement, as assessed by computed tomography (CT) scans, and C-reactive protein (CRP) levels." (PMID 39519310, 2024). "In this sense, IL-6 and CRP, which are pro-inflammatory molecules, were elevated in the serum of the COVID-19 patients in our study." (PMID 39057070, 2024). "In conjunction with this finding, we observed that MPO-DNA, H3cit, and H3cit-DNA complexes correlated with CRP and the neutrophil/lymphocyte ratio, both being key biological markers of disease severity in all COVID-19 patients." (PMID 38454482, 2024). "CRP is another marker of systemic inflammation that can contribute to the cytokine storm in severe cases of COVID-19." (PMID 39759701, 2024). "Then, through an extended MR study design, we sought to strengthen the evidence for a causal relation of blood levels of IL-6 pathway components, including IL-6, sIL6R, soluble IL6ST (also called gp130), and CRP, on COVID-19 outcomes." (PMID 39062668, 2024). "COVID-19 patients also revealed a major increase in C-reactive protein (CRP), IL-2, IL-4, IL-6, IL-10, TNF-α, and IFN-γ." (PMID 38540252, 2024). "This study finds that COVID-19 severity, liver cirrhosis, sex, age, leukocyte, NLR, CRP, creatinine, and procalcitonin are associated with COVID-19 mortality within 30 days." (PMID 38792539, 2024).
COVID-19 (continued). "Studies have also shown that patients with severe evolution of COVID-19 exhibit an association of lymphopenia with neutrophilia, as well as elevated values of LDH and CRP." (PMID 38392603, 2024). "Recent studies have shown that the severity or development of COVID-19 is related to plasma CRP levels." (PMID 39345300, 2024). "In an analysis excluding cancer patients, it was found that age, D-Dimer, CRP, and PCT were associated with 30-day mortality in COVID-19 patients, while steroid therapy is protective." (PMID 38792539, 2024). "Laboratory indicators at the time of COVID-19 diagnosis, including hemoglobin, albumin, lactate dehydrogenase, and C-reactive protein (CRP), showed substantial differences between the patients who survived and those who died." (PMID 38172385, 2024). "After MSC infusion, peripheral lymphocytes rose and C-reactive protein (CRP) levels fell in COVID-19 patients." (PMID 38650667, 2024). "CRP is another acute-phase protein that has been consistently elevated in patients with severe COVID-19." (PMID 39408010, 2024). "The comparative study of biological variables showed elevated values for CRP in COVID-19 versus PCI (28.90/8.72 mg/L; 82.22/58.48 mg/L; 131.30/58.48 mg/L) and LDH (554.56/284.12) for patients diagnosed in the year 2021." (PMID 38392603, 2024). "Previous reports have found that the median levels of CRP and IL-6 in patients infected with COVID-19 are 5.56 mg/L and 9.52 pg/mL, respectively." (PMID 39628680, 2024). "COVID-19 patients from this cohort presented increased CRP as well as ALT and GGT levels, a reduced international normalised ratio and lower albumin concentrations, indicating impaired hepatic synthesis function, whereas bilirubin was normal." (PMID 39408818, 2024). "Several research groups, primarily from China, have suggested that serum levels of ferritin, CRP, and procalcitonin are reliable predictors of mortality in patients with severe COVID-19." (PMID 38793085, 2024). "Patients with COVID-19 had higher CRP (11.8 vs. 5.2 mg/dl), ferritin level (537 vs. 386.2 ng/l) and hyponatremia (136 vs. 138 mmol/l) levels." (PMID 38649863, 2024). "The strong predictive value of CAR suggests that combining CRP with serum albumin enhances the assessment of inflammatory status and nutritional condition, which are critical factors in the prognosis of COVID-19 patients." (PMID 39767616, 2024). "A model based on laboratory indicators and physiological parameters shows that CRP, D-dimer, and RR can simply predict the 30-day outcome of patients with COVID-19." (PMID 39322989, 2024). "In this study, we identified the independent risk factors for new-onset CNS manifestations in patients with COVID-19 as being female sex, diabetes mellitus, lymphopenia, thrombocytopenia, and high titers of CRP and CK." (PMID 38999510, 2024). "Elevated CRP and ferritin levels in COVID-19 positive cases highlight systemic inflammatory responses triggered by the virus." (PMID 39767161, 2024). "As a result of severe COVID-19, blood cell counts are altered, including an increase in neutrophils and leukocytes, a rise in C-reactive protein (CRP), and a drop in lymphocytes and platelets." (PMID 38184750, 2024). "The ratio of C-reactive protein (CRP) to lymphocytes (CLR) is known to be an important prognostic marker for COVID-19, and cR has been shown to reduce serum C-reactive protein levels." (PMID 38915116, 2024). "In viral infections such as COVID-19, CRP levels can be significantly elevated due to the body's inflammatory response." (PMID 39840216, 2024). "IL-34, CRP, D-dimer, TnI, and ferritin levels were statistically significantly higher; albumin levels were statistically significantly lower in the COVID-19-positive group compared to the control group (p<0.05)." (PMID 38626032, 2024). "CRP, as a sensitive biomarker of inflammation, holds potential as an early predictor in patients affected by COVID-19." (PMID 38675414, 2024).
COVID-19 (continued). "This analysis included patients with severe and moderate COVID-19, with the latter having lower CRP and procalcitonin levels and fewer superinfections." (PMID 39273246, 2024). "In our study, significant elevation of IL-34 with CRP in COVID-19 seems to be compatible with previously reported results in terms of elevation of IL-34 in infections and inflammatory processes." (PMID 38626032, 2024). "In line with our findings, a recent meta-analysis assessing the use of O3FA in COVID-19 revealed a significant decrease in CRP serum levels." (PMID 39339646, 2024). "Research shows that high CRP levels combined with low saturation indicate a severe form of COVID-19." (PMID 39457522, 2024). "COVID-19 patients with elevated CRP and elevated (ADMA x SDMA) had a hazard ratio for mortality of 10.0 (1.56–64.23), p < 0.0001." (PMID 38977837, 2024). "IL-34 was elevated in correlation with CRP in COVID-19-positive cases, and higher accuracy rates were also observed than CRP." (PMID 38626032, 2024). "The chance of developing high values of C-reactive protein was 2.33 times higher in the group of patients with severe COVID-19 compared with patients with mild COVID-19." (PMID 37390087, 2023). "As a result, serum levels of CRP can predict the severity and progression of the disease in patients with COVID-19." (PMID 37415112, 2023). "Neutrophil (NEU%), monocyte (MONO% and MONO), mean corpuscular volume (MCV), mean platelet volume (MPV), platelet large cell ratio (PLCR) and C-reactive protein (CRP) were significantly increased in COVID-19 patients than that in healthy controls (p < 0.05)." (PMID 37630661, 2023). "Among them, however, the main predictors of death by severe COVID-19 patients were IL-6, CRP and platelet count but only during the first wave." (PMID 36817433, 2023). "Our data revealed that PAR is potentially better associated with COVID-19 disease severity than common inflammatory markers such as procalcitonin, WBC, NLR, and CRP, and is a strong independent risk factor for ICU admission." (PMID 36950410, 2023). "As expected, COVID-19 was characterized by high levels of systemic inflammation, as reflected by the acute phase reactant, CRP, which is produced by the liver in response to increased expression of IL-6." (PMID 37646024, 2023). "Among the severe cases, 39.4% of the COVID-19 subjects with high CRP (> 100 mg/L) died, while the mortality rate was only 14.3% among the cases with CRP less than 100 mg/L." (PMID 37388734, 2023). "Future studies with larger sample sizes should investigate the three-way interaction between BMI, CRP, and age in relation to COVID-19 patient outcomes." (PMID 38003780, 2023). "One early study found a significantly decreased D-dimer, ferritin, CRP, IL-6 and procalcitonin in COVID-19 patients who underwent PLEX." (PMID 37712090, 2023). "Netakimab treatment in patients with severe COVID-19 decreased inflammation (c-reactive protein (CRP) and IL-6) and significantly improved pulmonary structure and function, leading to reduced ICU requirement and mortality rate." (PMID 37075454, 2023). "In association with many metabolite clusters, biochemical cluster 2, which includes CRP, D-dimer, and ferritin, predicted the fatality of individuals with COVID-19." (PMID 36852984, 2023). "Among the possible damage caused by the cytokine storm, elevated C-reactive protein (CRP) concentration and subsequent mitochondrial damage have also been correlated with the onset of sarcopenia and frailty in COVID-19 patients." (PMID 36836568, 2023). "Reportedly, levels of CRP, serum ferritin, and procalcitonin were significantly increased according to severity of COVID-19, and increases in these inflammatory biomarkers indicate a high risk of severe illness and poor prognosis." (PMID 36619223, 2023). "A very strong correlation between the severity of COVID-19 with the D-dimer and C-reactive protein (p = 0.9) (p = 0.02) was found." (PMID 37390087, 2023).